SOX11 (SRY-box transcription factor 11)
Diseases named in the same sentence as SOX11 in open-access papers (continued):
Sharing a sentence is not in itself a finding about the gene and the disease.
neuroendocrine carcinoma (1 paper, 2022). A malignant neuroendocrine neoplasm composed of cells containing secretory granules that stain positive for NSE and chromogranin. "While SOX11 is more specific than the other four markers for diagnosis of high-grade neuroendocrine carcinomas (HG-NECs) because 1) None of LCCs (0/63), the most challenging non-NE tumor type for differential diagnosis due to overlapped morphology with LCNECs displayed SOX11 positivity." (PMID 34996493, 2022).
neuropathic pain (1 paper, 2021). Chronic pain caused by damage to nerve fibers. "In our study, we confirmed increased SOX11 expression in SNI-induced neuropathic pain using integrated bioinformatic analysis and experimental verification." (PMID 33584192, 2021).
Optic neuropathy (1 paper, 2021). "Understanding these effects of posttranslational modification of Sox11 in regulating regeneration in vivo suggests a potent therapeutic strategy for vision restoration in optic neuropathies." (PMID 33441400, 2021). "Thus, Sox11 and its SUMOylation site at K91 regulate gene expression, survival and axon growth in RGCs, and may be explored further as potential regenerative therapies for optic neuropathy." (PMID 33441400, 2021).
oral lichen planus (1 paper, 2025). Oral lichen planus is a chronic inflammatory oral condition of unknown aetiology characterized by T-cell-mediated chronic immune response and abnormal epithelial keratinization cycle. "Increased expression of the oncogenic Sox11, together with significantly reduced Sox11 promoter methylation, was observed in oral lichen planus (OLP)-associated OSCC." (PMID 40746882, 2025).
ovarian tumor (1 paper, 2015). "The proliferative subtype was identified by the overexpression of transcription factors HMGA2 and SOX11, proliferation marker genes such as MCM2 and PCNA, and underexpression of MUC1 and MUC16, which are known ovarian tumor marker genes." (PMID 25611546, 2015).
peripheral nerve injury (1 paper, 2019). Injury to a peripheral nerve. "It has been suggested that transcription factors such as ATF3, JUN and SOX11 may be important in the regulation changes in ion channel function and their accessory subunits after peripheral nerve injury." (PMID 31620455, 2019).
prostate tumor (1 paper, 2021). "SOX11 is hypermethylated in prostate tumor tissues and the hypermethylation is associated with aggressive clinical features, including higher PSA and Gleason scores." (PMID 34944472, 2021).
serous ovarian cancer (1 paper, 2023). "In summary, we report, for the first time, the potential involvement of SOX11 protein expression in the activation of EMT in serous ovarian cancer with a special focus on its association with tumor metastasis." (PMID 37760985, 2023). "In this regard, the results of our study indicate, for the first time, SOX11 overexpression as a possible factor that could interfere in the promotion of EMT in serous ovarian cancer, hence being involved in the mechanism’s underlying tumor metastasis." (PMID 37760985, 2023). "In view of these considerations, the present study aimed to investigate the potential role of SOX11 in metastatic serous ovarian cancer as a marker of EMT, as well as its influence on patients’ clinico-pathological characteristics including survival." (PMID 37760985, 2023).
squamous cell carcinoma of the cervix (1 paper, 2025). "Previous studies reported increased SOX11 expression in cervical squamous cell carcinoma and adenocarcinoma." (PMID 40626980, 2025). "Some studies report significant expression in the basal cells of the normal cervix and in LSIL, while others find SOX11 expression exclusively in squamous cell carcinoma of the cervix, with no expression in normal cervical tissue." (PMID 40626980, 2025).
Stroke (1 paper, 2024). Sudden impairment of blood flow to a part of the brain due to occlusion or rupture of an artery to the brain. "Our research findings suggest that Sox11 is crucial for neuronal survival under oxygen-glucose deprivation/reoxygenation (OGD/R) conditions and provides protection against stroke-induced damage." (PMID 39239553, 2024).
thyroid cancer (1 paper, 2022). "In detail, miR-211 modulates cells proliferation, migration and invasion by decreasing SOX11 in thyroid cancer." (PMID 35912006, 2022).
thyroid tumor (1 paper, 2019). A benign or malignant neoplasm affecting the thyroid gland. "Moreover, miR211 was indicated to inhibit the proliferation, migration, and invasion of thyroid tumor cells through downregulating SOX11." (PMID 31333725, 2019).
ventricular septal defect (1 paper, 2025). The presence of a defect (opening) in the septum that separates the two ventricles of the heart. "Mettl3 deficiency-induced downregulation of MEF2A, SOX4, and SOX11 expression could lead to congenital cardiac defects, including left pulmonary stenosis, ventricular septal defects, and right ventricular hypoplasia." (PMID 40303284, 2025).
tumor (119 papers, 2010 to 2026). "In human CRC samples, elevated SOX11 expression was associated with advanced tumor stages and worse prognosis." (PMID 40393982, 2025). "This transitional cell subpopulation expressed markers such as MYCN, EZH2, and SOX11 and was associated with rapid proliferation and tumour metastasis." (PMID 37887559, 2023). "Higher SOX11 expression in IDH1mt tumours was significantly associated with tumour grade (median mHS G2 = 7.5, G3 = 55, G4 = 47.6, p < 0.001, KW)." (PMID 37568909, 2023). "We found that high expression of SOX11 was significantly associated with tumor status in ACC, PRAD, UCEC and UVM." (PMID 36551589, 2022). "Aberrant SOX11 expression was closely associated with survival outcomes, stage, tumor recurrence, MSI, TMB and MMR-related genes." (PMID 36551589, 2022). "Larger tumours were also formed in the Sox11-deficient cohort in limiting dilution studies, and a statistically significant fivefold reduction in stem cell frequency was detected." (PMID 33969421, 2021). "SOX11 can be added to identify the aggressive MMs with risk for lymphatic dissemination and the presence of circulating tumor cells." (PMID 33801642, 2021). "Compared with mice transplanted with cells transduced with LentiCRISPRv2-GFP encoding a control sgRNA, animals xenografted with ASCL1 and SOX11 gene-edited cells survived longer, which was associated with reduced tumor PDGFRA expression at endpoint." (PMID 32142668, 2020). "SOX11 is a diagnostic and prognostic antigen in B cell lymphomas and has recently been demonstrated to have tumor suppressor functions." (PMID 30134837, 2018). "Recently, transcriptional activity of SOX11 was implicated in biological processes including B-cell differentiation, tumor angiogenesis, and overall pathogenesis of MCL." (PMID 29113297, 2017). "SOX11 is considered as a diagnostic and prognostic antigen in B cell lymphomas and has been demonstrated to have tumor suppressor functions." (PMID 24604109, 2014). "We showed that SOX11 is expressed and contributes to their maintenance in a self-renewal or proliferating progenitor state, as evidenced by our results showing that loss of SOX11 leads to a marked reduction in both in vitro growth and NB tumor xenograft growth in mice." (PMID 38653778, 2024). "Similarly, SOX11 has been implicated as a factor that can function as both a tumor suppressor and a metastasis inducer." (PMID 37509311, 2023). "SOCS1, CD274, and SOX11 associated with miR-155 and miR-215 in the regulation hub suggested exerting vital functions in tumor immunology, whether through the miR-155, miR-215 pathway or not." (PMID 35433461, 2022). "Mutation or deletion of SP140 was predictive for shorter PFS and OS and associated with SOX11 expression, suggesting this gene may be a potential tumor suppressor in MCL." (PMID 34882582, 2022). "In addition, high mRNA levels of SOX11 in HCC were closely associated with the high grade of the tumor." (PMID 36551589, 2022). "In most types of cancer, SOXC members could serve as the oncogenic role and poor prognostic value, however previous studies have been reported that the function of SOX11 was associated both with an oncogenic or tumor-suppressive role in carcinoma." (PMID 34442467, 2021). "Furthermore, ex vivo bioluminescence imaging and H&E staining showed that higher levels of tumour burden were detected in both the lungs and liver in the Sox11-deficient cohort." (PMID 33969421, 2021). "Previous studies have reported a direct association between tumor metastasis and SOX11 expression." (PMID 32586027, 2020). "Moreover, patients with SOX11 SNP rs77996007 with a genotype of TC and CC were significantly associated with large tumor size." (PMID 32586027, 2020). "Furthermore, the relative levels of SOX11 mRNA were significantly associated with the tumor status, clinical T status, and lymph node metastasis status in HNSCC tissues." (PMID 32586027, 2020).
tumor (continued). "SOX11 is a functionally associated protein in EOC with prognostic value for high-grade tumours." (PMID 21943380, 2011). "In addition, we found that high expression of SOX11 was significantly associated with tumor status in ACC, PRAD, UCEC and UVM, which indicated that SOX11 might have the potential to reflect tumor progression." (PMID 36551589, 2022). "Moreover, Sox11 overexpression has been shown to lead to cone genesis even after the normal cone genesis window; hence, their expression in the tumor cone clusters may suggest their involvement in the underlying cone-rich tumor phenotype in Rb." (PMID 34003213, 2021). "Stemness-related genes SOX4 and NFIA exhibited expression in both, mouse xenograft and hGliCS, with SOX11 showing high expression exclusively in hGliCS, compared to monocultured S24 tumor cells." (PMID 40188875, 2026). "Apparently, Sox11 is embedded in several distinct gene regulatory circuits, contributing to intestinal tissue homeostasis, tumor suppression, and TGF-β-mediated cancer cell invasion." (PMID 40393982, 2025). "Unexpectedly, aside from orchestrating the organoid response to TGF-β1, Sox11 controlled expression of genes related to normal gut function and tumor suppression." (PMID 40393982, 2025). "The methylation status of the Sox11 gene is also relevant to the prognosis and progression of tumours, which can be used as a useful biomarker for tumour diagnosis and prognosis evaluation." (PMID 39039706, 2024). "SOX11 has been identified with a high positive correlation with the tumor purity score (TPS), which is particularly upregulated in High TPS." (PMID 39457550, 2024). "Consistently, in a study from the European MCL Network with patients treated with ara-C containing regimens, cases with low SOX11 expression (<10% of SOX11+ tumor cells) had a shorter time-to-treatment failure and shorter overall survival than SOX11+ cases." (PMID 38237141, 2024). "Then, we analysed the ECAR and OCR of these tumour tissues; similarly, increased glycolysis flux mediated by Sox11 upregulation was entirely abolished by Sox11 knockdown." (PMID 39039706, 2024). "SOX11 is critical for neurogenesis and neuronal differentiation and also significantly contributes to cellular survival, promoting tumour cell proliferation, invasion, and resistance to apoptosis, which facilitates tumour malignancy and progression." (PMID 39457550, 2024). "Subsequently, the ATP assay of tumour tissue showed that Sox11 downregulation suppresses ATP generation, which was further reversed by overexpression of Sox11." (PMID 39039706, 2024). "Sox11 plays a pivotal role in regulating neuronal survival, making it a crucial regulatory factor in the development of sensory neurons and a factor in tumor stem cells." (PMID 39239553, 2024). "The fact that SOX11 was included in our protein network suggests that changes in its bulk RNA-seq expression could be driven by Letrozole treatment, though we are unsure whether this upregulation primarily takes place within tumor cells or in the tumor-associated immune cells." (PMID 39057065, 2024). "Nevertheless, in a limited number of malignancies, SOX11 has also been identified to function as a tumor suppressor." (PMID 36551589, 2022). "Here, the correlation between SOX11 expression and the tumor immune microenvironment was assessed using the ESTIMATE method." (PMID 36551589, 2022). "SOX11 exerts tumor-stimulative effects in various tumors by promoting cell survival and proliferation, and initiating metastasis angiogenesis." (PMID 35912006, 2022). "In many cancers, dysfunctional expression of SOX11 has been correlated with increased cancer cell survival, inhibition of cell differentiation and tumor progression." (PMID 36551589, 2022). "The significance of this study is to reveal the prognostic value of SOX11 in pan-cancer, which not only further supports previous findings but also contributes to our understanding of the multifaceted role of SOX11 in tumor progression." (PMID 36551589, 2022).
tumor (continued). "Third, only relevant analyses were performed in this study, and the molecular mechanisms of SOX11 in tumor stemness and immune infiltration require further investigation." (PMID 36551589, 2022). "The protein level of SOX11 in tumor tissues and tumor-adjacent tissues was verified by human pan-cancer tissue microarray." (PMID 36551589, 2022). "In a limited number of malignant tumors, SOX11 acts as a tumor suppressor by inhibiting cell proliferation and metastasis, as well as suppressing the maintenance of cancer-initiating cells." (PMID 35912006, 2022). "The transcription factor SOX11 has been shown to be a key oncogenic factor in MCL by promoting tumor growth in vivo by regulating B-cell differentiation pathways and controlling the cell cycle and apoptosis." (PMID 35804870, 2022). "In ACC, COAD, ESCA, TGCT and UVM, the expression of SOX11 showed an increasing trend with increasing tumor stage." (PMID 36551589, 2022). "A few tumor cells resided in a neural crest-like state, as identified by co-localized SOX11 and TFAP2B regulon activities, and exhibited a low level of melanocytic regulon activity compared to intermediate, except for SOX10." (PMID 35903095, 2022). "Literatures revealed the ambiguous role of SOX11 in predicting tumours prognosis, which is particularly dependent on cancer types." (PMID 34996493, 2022). "A tissue microarray was used to verify the difference in SOX11 expression among normal tissues, tumor tissues and corresponding tumor-adjacent tissues." (PMID 36551589, 2022). "Tumours with reduced Sox11 levels stained positive for both K14 and SMA in the normal mammary tissues adjacent to the tumour, which provided internal positive controls." (PMID 33969421, 2021). "Larger average tumour volumes (388 mm3) were observed in tumours with reduced Sox11 levels compared to control tumours (170 mm3) at 2 weeks post-injection." (PMID 33969421, 2021). "Reduction of E-cadherin and basal marker expression was observed in Brca1−/− tumours when Sox11 levels were reduced." (PMID 33969421, 2021). "In other tumors, SOX11 is reported to play a role as an oncogene or, in contrast, a tumor suppressor gene, depending on tumor type (Figure A1)." (PMID 33801642, 2021). "We found that reducing Sox11 levels in Brca1.3 cells led to reduced colony formation in two dimensions and reduced tumour sphere-forming efficiency in the presence of Matrigel when compared to control spheroids." (PMID 33969421, 2021). "Quantitative RT-PCR (RT-qPCR) revealed that genes representing mesodermal (T, Kdr), endodermal (Foxa2, Gata4/6, Sox17) and ectodermal (Fgf5, Sox11 for primitive ectoderm) differentiation were generally activated in tumor." (PMID 33468253, 2021). "We further examined the relationship between the level of SOX11 and tumor grade, as well as survival in BC." (PMID 32043610, 2020). "We found that SOX11+DCIS tumour cells metastasize to brain and bone at greater frequency and to lungs at lower frequency compared to cells with lower SOX11 levels." (PMID 32909943, 2020). "In MCL, conflicting reports have been made about the effect of knockdown or SOX11 overexpression on cell proliferation and tumor growth." (PMID 32029838, 2020). "Despite their smaller volume, tumours originated from cells with high SOX11 levels displayed greater bioluminescence than control tumours, suggesting iSOX11 tumours contained more viable cells." (PMID 32909943, 2020). "When injected directly into the mammary duct, iSOX11 DCIS cells formed slightly larger tumours, with similar bioluminescence levels as iEV tumours, which indicates the microenvironment highly influences behaviour of SOX11+ tumour cells." (PMID 32909943, 2020). "Immunochemistry staining showed more SOX11-positive cells in tumor tissues than that of adjacent normal tissues (P < 0.01)." (PMID 30134837, 2018).